INS (insulin)
Diseases named in the same sentence as INS in open-access papers (continued):
Sharing a sentence is not in itself a finding about the gene and the disease.
diabetes (continued). "In the KEGG pathway enrichment analysis, several significant pathways were related to diabetes, including AMPK signaling pathway, PPAR signaling pathway, insulin signaling pathway, and so on." (PMID 31338039, 2019). "Although 90–95% of DM patients are insulin-independent type (type 2 diabetes, T2D), the pancreatic islet undergoes a malfunction or dysfunction that results in a loss of an insulin-secretion ability during disease progression and leads to a need to replenish insulin." (PMID 31067805, 2019). "The insulin regimens that are commonly used for patients with type 1 diabetes mellitus are multiple daily insulin injections (MDI), premixed insulin and continuous subcutaneous insulin infusion (CSII)." (PMID 30938074, 2019). "The most widely accepted score for type 2 diabetes mellitus is the HOMA-IR index, which represents the product of glucose and insulin concentrations divided by a factor." (PMID 30841605, 2019). "Although research suggests diabetes is associated with increased postoperative morbidity after hip and knee replacement, the effect of diabetes and varying management with insulin versus non-insulin agents on total shoulder arthroplasty (TSA) is not established." (PMID 30621737, 2019). "The insulin-stimulated translocation of the GLUT4 transporter is reduced in insulin resistance and diabetes." (PMID 31516543, 2019). "This mouse model replicated diabetes and insulin resistance in people by exhibiting elevated IGF-1 and insulin levels, insulin resistance, and enhanced intimal hyperplasia when they are fed HFD vs. control." (PMID 31562314, 2019). "Type 2 Diabetes Mellitus (T2DM) is a group of metabolic diseases with characteristics of hyperglycemia that occur due to abnormal insulin secretion, insulin action or both." (PMID 31554278, 2019). "This CDSS can remotely monitor diabetics according to their real-time WBAN metrics, and suggests adjustments in insulin dosages, exercise plans, and diet plans." (PMID 31077222, 2019). "Type 2 Diabetes Mellitus (T2DM) is a chronic, progressive metabolic disorder characterized by hyperglycemia resulting from abnormalities in insulin secretion, insulin action, or both." (PMID 31969896, 2019). "Educational guidelines assist people with diabetes to understand the rationales for recommended interventions, such as: regular BGL monitoring; administration of insulin and oral hypoglycaemic medications; low sugar diet; and lifestyle changes." (PMID 30794570, 2019). "We observed that diabetes mellitus (DM) was identified in 39 patients with NAFLD, with insulin independent sub-type being more frequent in patients with moderate and severe FP (p value = 0.02 and p value = 0.01, respectively)." (PMID 31627351, 2019). "The 68 studies that examined diabetes/inflammation measures (HOMA-IR, insulin, glucose, C reactive protein, interleukin-6, alanine transaminase and the 71 studies examining cardiac measures (eg, lipids, cholesterol, blood pressure) will be reported separately." (PMID 31473614, 2019). "The TyG Index had a higher C-statistic for cf-PWV > 10 m/s and ba-PWV > 1800 cm/s but not for MAU or CKD after adjustment for age, sex, BMI, WC, smoking habit, hypertension, family history of premature CVD, diabetes, HDL-C, insulin therapy and statin therapy." (PMID 31345238, 2019). "While this observation is suggestive of increased patient satisfaction with V-Go over other insulin delivery devices, this interpretation is moderated by the observed baseline imbalance in TRIM-Diabetes Device Scores between treatment groups." (PMID 32685581, 2019). "Given continuous advances in diabetes care, including new medical treatments, technical aids for insulin administration and glucose monitoring, and support for self-management, research results on HRQOL in people with diabetes need to be continuously updated." (PMID 31412881, 2019).
diabetes (continued). "The factors found to be significantly associated with hypoglycemia included type 2 diabetes (AOR 0.34, 95%CI: 0.14, 0.82), duration of diabetes from 10 to 14 years (AOR 6.34, 95%CI: 2.12, 18.96) and insulin therapy (AOR 4.93, 95%CI: 2.05, 11.86)." (PMID 30700277, 2019). "We adapted the Rapid Assessment Protocol for Insulin Access (RAPIA) to evaluate the impact of the BoP, a public–private partnership that aims to facilitate access to diabetes care in Kenya." (PMID 31116677, 2019). "GLP-1, an endogenous polypeptide hormone released in response to food intake, potentiate insulin secretion from pancreatic cells through binding and activation of its receptor, and GLP-1R agonists have emerged as treatment options for type 2 diabetes mellitus." (PMID 30795583, 2019). "In addition, cases of noninsulinoma pancreatogenous hypoglycemia due to excessive insulin secretion, regardless of the presence/absence of underlying diabetes mellitus, have been reported, at least partly explaining the episode of hypoglycemia in patients receiving DPP-4 inhibitors alone." (PMID 30815039, 2019). "High-fat diet/low-dose STZ injections induce models of type 2 diabetes mellitus (T2DM), while two days of injection with STZ (45 mg/kg) into rats severely impaired insulin secretion and produced type 1 diabetes." (PMID 31001561, 2019). "There is a highly variable rate of decline in β-cell function after diagnosis of type 1 diabetes mellitus (T1DM); many patients retain detectable insulin secretion for years or decades." (PMID 31803138, 2019). "The other patients with type 2 PGDM had 3 years duration of diabetes, a pre-pregnancy HbA1c of 8% and mean HbA1c of 7% and were treated with NPH insulin and lispro." (PMID 31776421, 2019). "Diabetes mellitus (DM), a chronic metabolic disease, may impair insulin secretion, insulin action, or both." (PMID 32184883, 2019). "Patients with type 1 diabetes mellitus (T1DM) and severe cases of type 2 diabetes mellitus (T2DM) require daily injection of insulin." (PMID 31438545, 2019). "Type 2 diabetes mellitus (T2DM), which accounts for 85–95% of all cases, is characterized by insulin resistance (IR) in insulin-responsive tissues and impaired insulin secretion from the pancreatic β cell." (PMID 31455405, 2019). "In this study, we wished to investigate the effect of lysine demethylase inhibition in vivo on experimental diabetes and elucidate the specific role of KDM5B on insulin secretion." (PMID 31467927, 2019). "The concept of IR was introduced by Himmsworth in 1936 who showed that diabetes could be subdivided into two categories—insulin-sensitive and insulin-insensitive types —and this was later confirmed by Yalow and Berson with the novel measurement of insulin itself." (PMID 31331009, 2019). "Furthermore, increased ALT may predict reduced insulin sensitivity and diabetes." (PMID 31534560, 2019). "Despite glycemic control through restoration of insulin levels, T1DM subjects display increased cardiovascular disease (CVD) similar to that observed in type 2 diabetes mellitus (T2DM) subjects." (PMID 31299986, 2019). "Different proportions of Jiaotai Pill enhance PI3K pathway insulin signaling by upregulating the expression of the PI3K p85 subunit in skeletal muscle, attenuating the development of diabetes in a rat model of T2D." (PMID 31258478, 2019). "Type 2 diabetes mellitus (DM) is a metabolic disease characterized by reduced insulin sensitivity and increased insulin resistance, β cell dysfunction especially in glucose-induced insulin secretion, and elevated hepatic glucose production." (PMID 31557884, 2019). "MiR-320 is currently considered as a potential target for type 2 diabetes mellitus therapy since it regulates the expression of phosphoinositide-3-kinase (PI3K), a downstream mediator of insulin signaling." (PMID 31920988, 2019).
diabetes (continued). "In the top 20 enriched pathways, insulin signaling pathway, AMPK signaling pathway, glycerophospholipid metabolism, insulin resistance, and FoxO signaling pathway related to metabolism and diabetes were identified." (PMID 31338039, 2019). "Our previous study demonstrated that mesenchymal stem cells (MSCs) attenuated chronic inflammation in type 2 diabetes mellitus (T2DM), resulting in improved insulin sensitivity and islet function." (PMID 31747961, 2019). "Insulin and HOMA levels were significantly higher in participants with obesity and diabetes than in lean participants." (PMID 31203378, 2019). "Particularly, one animal study indicated that GABA acts as activator of insulin secretion, given that GABA-like immunoreactive cells in the pancreas of rats are reduced in diabetes." (PMID 31138673, 2019). "In the diabetes and DKD groups, although the insulin levels decreased compared to that in the IGT group, they were still higher than that in the NGT group." (PMID 31737684, 2019). "Type 2 diabetes mellitus (T2DM), also known as noninsulin-dependent DM, affects more than 90% of the diabetics and/or leads to serious lipid and protein metabolism disorders, with a characteristic of hyperglycemia and insulin resistance (IR), which is caused by impaired insulin secretion." (PMID 31885645, 2019). "Excluded participants were older, had a higher body temperature, were more frequently women or presented with diabetes, had higher BMI, waist and hip levels and had higher hs-CRP and insulin levels." (PMID 30250242, 2019). "Body mass index (BMI), as well as multiple metabolic parameters including the presence of diabetes, insulin resistance (HOMA-IR), and fasting insulin, was significantly higher in obese compared to lean patients." (PMID 30719456, 2019). "People who were treated with insulin injection and a combination of insulin and oral medication tended to have poor HRQOL in the domain of other health problems and diabetes complication." (PMID 31796044, 2019). "The groups were defined as insulin sensitive with normal glucose (IS-NGT), insulin resistant with normal glucose (IR-NGT), impaired fasting glucose (IFG), impaired glucose tolerance (IGT), and new diabetes (NDM)." (PMID 31779625, 2019). "Type 2 diabetes mellitus (T2DM) is sustained by insulin resistance (IR) and reduced β-cell mass, which is largely due to insulin secretory dysfunction." (PMID 31890678, 2019). "Diabetes was induced by Streptozotocin (STZ) (60 mg/kg, IP); insulin (5 mU/animal, 5 μl) was injected into the left ventricle." (PMID 31579448, 2019). "We also found that newer diabetes medications (DPP4 inhibitors, GLP-1 receptor agonists, and SGLT2 inhibitors) were all continued in the vast majority of participants initiating insulin." (PMID 30759121, 2019). "Type 2 diabetes (T2D), caused by altered insulin function, and also defined as non-insulin-dependent diabetes mellitus occurs in 90%–95% of DM patients." (PMID 31540445, 2019). "Type 2 diabetes mellitus (T2DM) makes up 90–95% of all diabetes and is characterized by chronic hyperglycemia due to impaired target tissue response to insulin (i.e., insulin resistance) and progressive deterioration of pancreatic β-cell function." (PMID 31248127, 2019). "As an analog of GLP-1, which was first authorized to treat type 2 diabetes mellitus, exenatide can bind to the GLP-1R of pancreatic β-cells promoting the secretion of insulin." (PMID 31611738, 2019). "Some evaluations have suggested that the most marked improvements in insulin sensitivity and glucose metabolism are achieved in patients with higher baseline HOMA-IR levels and established diabetes, respectively." (PMID 30884773, 2019). "Type 2 diabetes mellitus (T2DM) is mainly characterized by insulin resistance (IR) and impaired insulin secretion." (PMID 31455405, 2019).
diabetes (continued). "In addition, experimental studies have shown that tea could protect against diabetes mellitus and diabetic complications by improving insulin resistance, activating the insulin signaling pathway, playing an insulin-like role, improving oxidative stress, and alleviating inflammatory response." (PMID 31185622, 2019). "Insulin sensitizers TZD, known as PPAR-γ agonists, represent one of the antidiabetic drug options to directly reduce insulin resistance in patients with diabetes mellitus." (PMID 31027492, 2019). "The UK Prospective Diabetes Studies (UKPDS), designed to demonstrate that insulin was better than diet advice for preventing diabetic complications, was unable to help to establish a safe glucose goal." (PMID 31249634, 2019). "To characterize the molecular alterations of pancreatic alpha cells in diabetes; we generated DIO hyperglycemic mice using GLU-Venus x INS-Cherry transgenic mice." (PMID 30849121, 2019). "In a study of pancreatic perfusion, the administration of insulin suppressed glucagon secretion in dogs with alloxan-induced diabetes and in rats with STZ-induced diabetes." (PMID 31357734, 2019). "By this criterion, three of the four tested dogs, VSH-02, WSU-01 and WSU-02, appear to have autoimmune diabetes, while VSH-01 may have an “insulin resistant” form of insulin-dependent DM." (PMID 31536503, 2019). "Among the total number of cases, more than 90% are represented by the type 2 diabetes mellitus (T2DM), characterized with impaired insulin action and/or insulin secretion." (PMID 31083443, 2019). "Patients in the V-Go as well as the STO group were generally satisfied with their insulin delivery device at baseline and EOS, with average TRIM-Diabetes Device scores in the 70s and 80s on a 100-point scale." (PMID 32685581, 2019). "Moreover, data implicating pancreatic β cell primary cilia in the regulation of insulin secretion raise the possibility that a ciliary defect contributes to the progressive failure of insulin secretion that occurs in AS and is the major factor in progression to diabetes." (PMID 30421101, 2019). "In conclusion, upregulation of serine 473 phosphorylation by NS5A of HCV genotype 3a suggests that this gene impairs the normal insulin AKT/PKB signaling pathway that leads towards insulin resistance and Type 2 diabetes mellitus." (PMID 30992506, 2019). "Given its potential role in insulin signaling, we examined the expression of NR6A1 in the livers of diabetes-resistant db/db mice and Goto-Kakizaki (GK) rats." (PMID 31315616, 2019). "This analysis evaluates the cost-effectiveness of insulin degludec (degludec) versus biosimilar insulin glargine U100 (glargine U100) in patients with type 1 (T1DM) and type 2 diabetes mellitus (T2DM) in Bulgaria." (PMID 31796048, 2019). "Diabetes mellitus (DM) is a chronic disease that occurs when there are increased levels of blood glucose because the body is unable to produce any or enough of the hormone insulin or use insulin effectively." (PMID 31354628, 2019). "Since age, body mass index (BMI), diabetes duration, fasting plasma glucose (FPG), glycated hemoglobin (HbA1C), and insulin are important indicators in the progression of T2D, the correlation between the PD-1 expression and these indicators was evaluated." (PMID 31008114, 2019). "In a previous study on diabetes, EB was used to suppress VNUT-mediated ATP release, followed by lower glucose and insulin secretion." (PMID 31505901, 2019). "In addition, Walker’s paper found that insulin treated type 2 diabetic patients and type 1 were at an equal risk of severe hypoglycaemic episodes (SHEs), although the authors do not adequately address diabetes managed by diet or oral medications." (PMID 33328832, 2019). "Diabetes mellitus (DM) is a metabolic disorder characterized by chronic hyperglycemia either because the pancreas does not produce enough insulin or the peripheral target tissues are unable to respond to the normal concentration of insulin." (PMID 31583253, 2019).
diabetes (continued). "In Type 2 diabetes mellitus (T2DM), pancreatic insulin secretion and insulin sensitivity become impaired, compounded by excessive gluconeogenesis, which leads to chronic dysglycemia." (PMID 31372175, 2019). "Metformin, a first-line pharmacotherapy for treatment of diabetes, is a potent activator of AMPK with insulin sensitizing effects." (PMID 31920962, 2019). "The colonization of Lachnespiraceae (strain AJ110941) to germ free ob/ob rats, induced significant adipose tissue weight, blood glucose levels, and plasma insulin levels, indicating that AJ110941 was related to the development of obesity and diabetes." (PMID 31064150, 2019). "Age, sex, duration of diabetes, BMI, BP, HDL-C, LDL-C, and insulin treatment were comparable among the three groups." (PMID 31379940, 2019). "Type 2 diabetes mellitus (T2DM) is the world’s most common metabolic disease and is characterized by insulin secretion defects, which are influenced by lifestyle factors such as age, pregnancy, and obesity and have a strong genetic component." (PMID 31835423, 2019). "Diabetes mellitus (DM) is defined by hyperglycemia resulting from defects in insulin secretion, insulin action, or both, classified as type 1 diabetes (type 1 DM), type 2 diabetes mellitus (type 2 DM), other specific types of diabetes mellitus, and gestational diabetes." (PMID 30818888, 2019). "FGF21 is known to regulate insulin sensitivity and body weight, and circulating serum FGF21 concentration increases as a result of FGF21 resistance in obesity and diabetes." (PMID 31323977, 2019). "Finally, using the regression model, we tested our primary hypothesis that executive functions and clinical factors (age, sex, metabolic control, self-management, treatment regimen, insulin dose) are related to the readiness to change in adolescents with diabetes." (PMID 31183368, 2019). "Candidate target genes also included six genes involved in MODY and other monogenic and syndromic forms of diabetes (ABCC8, KCNJ11, GCK, INS, GLIS3, WFS1)." (PMID 31064983, 2019). "MiR-320 is currently considered as a promising target for the treatment of type-2 diabetes mellitus and regulates the expression levels of the p85 subunit of the PI3K which enhances adipocyte insulin sensitivity in obesity." (PMID 31920988, 2019). "Diabetes was induced by streptozotocin (50 mg/kg; i.p), EAPR (250 & 500 mg/kg; b.wt) and standard Insulin (6 IU/animal; subcutaneous; o.i.d) were administered to the diabetic rats." (PMID 29904686, 2018). "For clinical phenotype, f-GADA-positive individuals were diagnosed with diabetes at a median age of 47.0 years (IQR 38.4–55.7 years), median BMI of 25.6 kg/m2 (IQR 22.8–29.4 kg/m2) and 51.2% required insulin therapy." (PMID 29619531, 2018). "In fact, severe hypoglycaemia is more frequent in CHI patients with diabetes than in patients with T1DM, probably due to unregulated release of insulin from the remaining, yet malfunctioning beta cells." (PMID 30577875, 2018). "It is reported that despite insulin therapy, overt nephropathy and severe retinopathy were, respectively, developed in 7 to 30% and 24 to 47% of the T1DM patients in a diabetes clinic of a developed country after 25 years." (PMID 29373983, 2018). "Another systematic review of ginseng-related therapies in type 2 diabetes mellitus (T2DM)T2DM showed the benefit of ginseng supplementation in improving glucose control and insulin sensitivity in patients with T2DM or impaired glucose intolerance." (PMID 30705884, 2018). "Therefore, SITA patients were more often female, and more likely to have comorbidities such as insulin treated Diabetes(DM), DM with end organ damage, neurologic dysfunction and unstable angina." (PMID 30102699, 2018). "Ribosomal translation, insulin synthesis and processing, diabetes pathways and ATF6-controlled UPR chaperones gene sets were overrepresented among the genes upregulated in INS C96R cells." (PMID 30412052, 2018).